RN7SL174P (RNA, 7SL, cytoplasmic 174, pseudogene)
Gene: Miscellaneous RNA gene on chromosome 5 (119,306,343 to 119,306,631, reverse strand). Ensembl gene ENSG00000243333.
Homologues: Orthologues: chimpanzee Metazoa_SRP (98% identical), macaque Metazoa_SRP (94% identical). Paralogues in human: RN7SL1 (86% identical), RN7SL2 (86% identical), RN7SL3 (85% identical), RN7SL45P (83% identical), RN7SL118P (82% identical), RN7SL709P (82% identical), RN7SL448P (82% identical), RN7SL478P (82% identical), RN7SL492P (81% identical), RN7SL126P (81% identical), RN7SL242P (81% identical), RN7SL480P (81% identical), and 704 more.